SPATA22 (spermatogenesis associated 22)
Description:
Meiosis-specific protein required for homologous recombination in meiosis I.
Synonyms: NYD-SP20; NYDSP20; POF25; SPGF96
Tractability: No criterion of Open Targets' tractability assessment is met for any kind of drug.
Gene: Protein-coding gene on chromosome 17 (3,440,019 to 3,513,852, reverse strand). Ensembl gene ENSG00000141255.
Subcellular location: Chromosome
Gene Ontology:
Molecular function: protein binding
Biological process: regulation of meiotic cell cycle; gamete generation; homologous chromosome pairing at meiosis; meiotic DNA repair synthesis
Cellular component: nucleus; chromosome
Genetic constraint (gnomAD): Loss-of-function variants: 15 observed, 25.3 expected, observed/expected ratio (o/e) 0.59, 90% interval 0.4 to 0.91. The upper end of that interval is the gene's LOEUF score, 0.91, which puts it in group 3 of 6, group 1 being the genes least tolerant of losing a copy. Missense variants: 258 observed, 281.27 expected, observed/expected ratio (o/e) 0.92, 90% interval 0.83 to 1.02. Synonymous variants: 90 observed, 95.03 expected, observed/expected ratio (o/e) 0.95, 90% interval 0.8 to 1.13.
Homologues: Orthologues: chimpanzee SPATA22 (98% identical), macaque SPATA22 (95% identical), dog SPATA22 (79% identical), pig SPATA22 (79% identical), guinea pig SPATA22 (76% identical), rabbit SPATA22 (76% identical), mouse Spata22 (72% identical), rat Spata22 (67% identical), tropical clawed frog spata22 (37% identical), zebrafish spata22 (29% identical).
Diseases named in the same sentence as SPATA22 in open-access papers:
SPATA22 is named in the same sentence as 10 diseases in open-access papers, as found by Europe PMC text mining. Sharing a sentence is not in itself a finding about the gene and the disease. The quoted sentences say what the papers report.
Infertility (2 papers, 2022 to 2023). "Homozygous spermatogenesis associated 22 (SPATA22) is a sex-related gene associated with infertility and related traits." (PMID 35681846, 2022). "Both mutations affect the expression of the MEIOB binding domain of SPATA22, resulting in the improper binding of the two and leading to meiotic failure and infertility." (PMID 37430352, 2023).
Azoospermia (1 paper, 2013). Absence of any measurable level of sperm,whereby spermatozoa cannot be observed even after centrifugation of the semen pellet. "In this work, we used the specimens from testicular biopsies of men with non-obstructive azoospermia who underwent TESE to investigate the expression of spermatogenesis-related genes MND1, SPATA22, GAPDHS and ACR." (PMID 23675907, 2013).
clear cell renal cell carcinoma (1 paper, 2022). "A search against COSMIC identified a number of mutations found in tumors (i.e. adenocarcinoma, squamous cell carcinoma, malignant melanoma and clear cell renal cell carcinoma) localizing within fragments corresponding to SPATA22, ZBTB17, CCT7, MAP1S and PDIA3 proteins." (PMID 35205757, 2022).
cancer (2 papers, 2016). A tumor composed of atypical neoplastic, often pleomorphic cells that invade other tissues. "Meiosis Specific with OB Domains (MEIOB) was recently shown to be a DNA binding exonuclease essential for meiotic recombination in synergy with SPATA22, and this protein has been detected in different types of cancer cells." (PMID 27275820, 2016). "The co-factor for MEIOB (SPATA22) in meiosis recombination, which was co-expressed with MEIOB in testis, displayed mutually exclusive expression pattern in samples with LUAD and other cancer types." (PMID 26813108, 2016). "Importantly, there was a positive correlation between MEIOB and the genome-wide burden of focal copy number aberrations among samples from 10 cancer types with activation of MEIOB and SPATA22 expression." (PMID 27275820, 2016). "In addition, the expression of MEIOB was positively correlated with the genome-wide burden of focal copy number aberrations (CNAs) among samples from 10 cancer types with MEIOB and SPATA22 activation (Spearman's rank correlation coefficient=0.12, P=8.30 × 10−14)." (PMID 26813108, 2016).
tumor (2 papers, 2016 to 2019). "We also observed similar MEIOB and SPATA22 activation in other tumour types." (PMID 26813108, 2016). "Among them were known cancer/testis antigen genes (PNMA5, SPATA22, ROR1, and CT45A6) and some new candidates (PAX2, HES4, PEG10, NTN4, PDE10A, and POSTN), these genes could be useful tumor markers and potential therapeutic targets." (PMID 30922328, 2019).
SPATA22 also shares sentences with these, for which no sentence is quoted: adenocarcinoma (1 paper); male infertility (1); malignant melanoma (1); oligospermia (1); squamous cell carcinoma (1).